RAB11FIP1 (RAB11 family interacting protein 1)
Description:
A Rab11 effector protein involved in the endosomal recycling process. Also involved in controlling membrane trafficking along the phagocytic pathway and in phagocytosis. Interaction with RAB14 may function in the process of neurite formation.
Synonyms: Rab11-FIP1; RCP; FLJ22622; FLJ22524; NOEL1A
Tractability: Small molecule: a structure with a bound ligand is known. PROTAC: ubiquitination databases record sites on it; its protein half-life has been measured.
Gene: Protein-coding gene on chromosome 8 (37,858,618 to 37,899,513, reverse strand). Ensembl gene ENSG00000156675.
Subcellular location: Recycling endosome; Cytoplasmic vesicle; Cytoplasmic vesicle, phagosome membrane (Isoform 2)
Subcellular location (Human Protein Atlas): Vesicles
Gene Ontology:
Molecular function: protein binding; small GTPase binding
Biological process: negative regulation of adiponectin secretion; regulated exocytosis
Cellular component: cytoplasmic vesicle; recycling endosome; phagocytic vesicle membrane
Genetic constraint (gnomAD): Loss-of-function variants: 47 observed, 78.05 expected, observed/expected ratio (o/e) 0.6, 90% interval 0.48 to 0.77. The upper end of that interval is the gene's LOEUF score, 0.77, which puts it in group 3 of 6, group 1 being the genes least tolerant of losing a copy. Missense variants: 1,499 observed, 1,586.3 expected, observed/expected ratio (o/e) 0.94, 90% interval 0.9 to 0.99. Synonymous variants: 662 observed, 652.65 expected, observed/expected ratio (o/e) 1.01, 90% interval 0.95 to 1.08.
Homologues: Orthologues: chimpanzee RAB11FIP1 (99% identical), macaque RAB11FIP1 (93% identical), dog RAB11FIP1 (71% identical), rat Rab11fip1 (64% identical), mouse Rab11fip1 (62% identical), guinea pig Rab11fip1 (39% identical), tropical clawed frog rab11fip1 (26% identical), zebrafish rab11fip1a (13% identical), Drosophila melanogaster Rip11 (12% identical), Caenorhabditis elegans rfip-2 (8% identical). Paralogues in human: RAB11FIP5 (23% identical), RAB11FIP2 (17% identical).
Diseases named in the same sentence as RAB11FIP1 in open-access papers:
RAB11FIP1 is named in the same sentence as 13 diseases in open-access papers, as found by Europe PMC text mining. Sharing a sentence is not in itself a finding about the gene and the disease. The quoted sentences say what the papers report.
breast carcinoma (6 papers, 2010 to 2018). "The Rab coupling protein (RCP) or Rab11 family interacting protein 1 (Rab11FIP1), which is a Rab25 effector, is also well known as a breast cancer promoting gene." (PMID 25472813, 2015). "The RAB-coupling protein (RAB11FIP1) is a driving force for the 8p11-12 amplicon in human breast cancer and mouse xenograft models of mammary carcinogenesis." (PMID 21143914, 2010). "Additionally, Rab11Fip1/RCP is an oncogene in breast cancer, triggering activation of the Ras-MAPK pathway." (PMID 27259233, 2016). "This include the Steroid 5-alpha-reductase SRD5A1, the CCR4-NOT component RQCD1 and the Rab11 effector protein RAB11FIP1 which have all been reported as up-regulated in breast cancers." (PMID 22691140, 2012). "The list of effectors of Rab25 are increasing and while Rab11Fip1 or RCP was found to be a functional accomplice of Rab25 in luminal B cancers and is key for better stratification of luminal B patients, we are yet to understand the dynamics of Rab25-RCP in the other breast cancer subtypes." (PMID 27259233, 2016).
breast tumour (1 paper, 2024). "Similarly, both overexpression and downregulation of RCP (Rab11FIP1) have been reported to promote breast tumour progression." (PMID 38638676, 2024).
esophageal cancer (1 paper, 2021). A primary or metastatic malignant neoplasm involving the esophagus. "In esophageal cancer, RAB11FIP1 regulates EMT by directly inhibiting the key transcription factor ZEB1 of EMT." (PMID 34764984, 2021).
hearing loss (1 paper, 2018). "In a recently published study, our group showed that a Single Nucleotide Polymorphism (SNP) of the Rab11 effector Rab11Fip1 is associated with a noise-induced hearing loss." (PMID 29760588, 2018).
pancreatic cancer (1 paper, 2023). "In addition to protein levels, NSD3 induces global H3K36 dimethylation in pancreatic cancer cells and influences the mRNA levels for genes including ADAM28, ADAM9, BIRC3, CXCL5, DUOX2, GABRP, ITGB6, and RAB11FIP1." (PMID 37062069, 2023).
cancer (17 papers, 2013 to 2024). A tumor composed of atypical neoplastic, often pleomorphic cells that invade other tissues. "Indeed, Rab GTPases are key regulators of the endomembrane transport, and the Rab 11 effector Rab-coupling protein (RCP) (also known as RAB11FIP1), drives the 8p11-12 amplicon, which is associated with poor cancer outcomes." (PMID 40047887, 2024). "The Rab11 effector protein Rab11-family-interacting protein (FIP) 1 [RAB11FIP1; also known as Rab-coupling protein (RCP)] is similarly implicated in cell migration, invasion and cancer progression." (PMID 37232246, 2023). "Rab11FIP1, also known as Rab coupling protein (RCP) targets to vesicles trafficking through invasive pseudopodia of cancer cells via interaction with phosphatidic acid generated by diacylglycerol kinase α." (PMID 30622149, 2019). "PA is a necessary co-factor for the activity of diverse proteins, such as Raf family proteins, PKC-ζ, RAB11FIP1, PLC-β, SOS and mTOR, which have been implicated in cancer cell proliferation, survival, and tumorigenesis." (PMID 24205284, 2013).
tumor (10 papers, 2019 to 2025). "Recent findings suggest that RAB11FIP1 regulates organoid formation, tumor cell invasion, and EMT." (PMID 34764984, 2021). "Among the DEGs, we detected some marker genes (CD74, RAB11FIP1, and CST3) related to tumor invasion which are highly expressed in region C3." (PMID 40639417, 2025).
infection (2 papers, 2020). The state of being infected such as from the introduction of a foreign agent such as serum, vaccine, antigenic substance or organism. "We selected Rab5b, Rab11b, Rab8b and Rab11FIP1 for further characterisation in response to a ΔsdhA infection." (PMID 32096265, 2020).
RAB11FIP1 also shares sentences with these, for which no sentence is quoted: lung carcinoma (2 papers); ovarian carcinoma (2); dyslexia (1); head and neck squamous cell carcinoma (1); neuromuscular disease (1).